STAT3 (signal transducer and activator of transcription 3)
Diseases named in the same sentence as STAT3 in open-access papers (continued):
Sharing a sentence is not in itself a finding about the gene and the disease.
Obesity (continued). "This is a very important pathway in obesity since increased circulating leptin levels lead to development of leptin resistance by chronic activation of JAK/STAT3 in the CNS, whereas in the peripheral organs chronic IL-6-induced JAK/STAT3 impairs insulin action." (PMID 29170528, 2017). "Previous work from our laboratory showed that OSMR-β could regulate obesity-induced metabolic disorders of hepatic and cerebral ischemia/reperfusion injury in a STAT3-dependent manner." (PMID 28258089, 2017). "Moreover, newly identified cancer‐promoting functions of STAT3 – its role in mitochondria, epigenetic regulation, cancer stem cells, obesity, and premetastatic niches – further highlight the importance of targeting STAT3 in cancers." (PMID 28084011, 2017). "However, several other relevant pathways for lactation were also enriched such as STAT3 pathway, leptin signalling in obesity and NF-κB signalling." (PMID 28317898, 2017). "Thus, using HFD-ThrbPV/PVPten+/−mice, we have shown that inhibition of the STAT3 activity would be a novel treatment strategy for obesity-induced thyroid cancer." (PMID 27145454, 2016). "Furthermore, the importance of Ob-Rb–STAT3 signals from leptin receptors was demonstrated by the replacement of Tyr 1138 in Ob-Rb with a serine residue, which specifically disrupted Ob-Rb–STAT3 signaling in mice, resulting in obesity." (PMID 27375555, 2016). "Recent evidence also suggests that inhibition of the STAT3 activity may be a treatment strategy for obesity-induced thyroid cancer." (PMID 27050378, 2016). "It would be interestingly to test whether a higher STAT3 activity would be also observed in patients with a high glucose level such as cancer patients with diabetes or obesity." (PMID 27101310, 2016). "The STAT3 signaling pathway is involved in thyroid cancer aggravated by obesity-related metabolic changes and may be a potential therapeutic target in thyroid cancer." (PMID 27050378, 2016). "While constitutive STAT3 activity had initially been attributed to deregulated growth factor signaling, recent studies have identified STAT3 as an important mediator of carcinogenesis driven by chronic inflammation, obesity and/or metabolism, cancer stem cells (CSCs)." (PMID 27049829, 2016). "Besides, mice with a pancreatic beta-cell-specific disruption of the STAT3 gene exhibited an increase in appetite and obesity, and partial leptin resistance and glucose intolerance." (PMID 25014397, 2014). "Here we explore whether STAT3 common variations influence risks of obesity and other metabolic disorders in a Chinese Han population." (PMID 25014397, 2014). "Our observations further confirm the involvement of STAT3 in regulation of energy homeostasis and lipid metabolism and indicate the potential for STAT3 to serve as a target for controlling the development of obesity and other metabolic disorders." (PMID 25014397, 2014). "These facts strongly link STAT3 protein with obesity and insulin resistance." (PMID 23110196, 2012). "Interestingly, recent studies suggest that STAT3 activation is also implicated in HCV- and obesity-mediated hepatocarcinogenesis." (PMID 22136659, 2011). "Moreover, targeting Stat3 in myeloid cells may be a novel approach to ameliorate obesity-induced insulin resistance." (PMID 40801626, 2025). "We then examined whether Stat3 in myeloid cells mediates obesity-induced insulin resistance." (PMID 40801626, 2025). "Notably, leptin-treated NachBac mice showed a p-STAT3 expression level comparable to that of leptin-treated ob/ob mice, demonstrating that, despite severe obesity development and phenotypic leptin resistance, leptin-induced p-STAT3 signaling remains intact in Arc LepR neurons." (PMID 40540394, 2025). "This suggests that obesity caused by caponization is closely related to LEP resistance, similar to a previous finding that exogenously administered LEP did not induce a signal transducer and activator of transcription 3 (STAT3) phosphorylation and or increase SOCS3." (PMID 39201373, 2024).
Obesity (continued). "Additionally, emerging evidence suggests that both SP1 and STAT3 can suppress the expression of pivotal genes implicated in adipocyte differentiation, including PPARγ, C/EBPα, and FABP4, thereby potentially restoring insulin sensitivity and mitigating obesity." (PMID 37445596, 2023). "Moreover, specific deletion of STAT3 in neurons also results in profound obesity in mice." (PMID 38027481, 2023). "Moreover, the development of liver cancer promoted by obesity depends on the production of tumor promoting cytokines IL-6 and TNF, which can cause liver inflammation and activation of oncogenic transcription factor STAT3." (PMID 35422001, 2022). "Moreover, excess STAT3 activity inhibited POMC expression in the hypothalamus of diet-induced obesity mice, implying that STAT3 inhibition may promote leptin signaling." (PMID 34944525, 2021). "Leptin-activated STAT3 phosphorylation, as proved in the hypothalamus of lean wild-type animal, becomes a marker frequently employed in the assessment of central leptin signaling in the case of leptin resistance, similar to the situation in most obesity of humans and rodents of DIO." (PMID 33849593, 2021). "Disrupting LepRb-STAT3 signalling in mice causes hyperphagia and obesity, but not infertility." (PMID 34502119, 2021). "Therefore, it is worthy to examine whether JAK2/STAT3 pathway is involved in molecular mechanisms of obesity-induced cardiac hypertrophy." (PMID 30940158, 2019). "Activating α7-nAChR may not only reduce obesity related insulin resistance by anti-inflammation mechanism, but also ameliorate non-obese or low inflammation related insulin resistance through STAT3 related direct or indirect pathway." (PMID 23251458, 2012). "Collectively, these findings suggest that EA prevents HFD-induced obesity by alleviating intestinal oxidative stress and mitochondrial dysfunction through the modulation of the PPARG/STAT3/p-AKT1 signaling axis." (PMID 41829165, 2026). "Taken together, our data suggest that leptin doses mimicking hyperleptinemia in individuals with obesity were able to activate NCOA1, contributing to the activation and phosphorylation of the JAK2/STAT3 pathway." (PMID 41562922, 2026). "In leptin-deficient or leptin-resistant HFD models, circulating levels of IL-4 decrease, leading to metabolic abnormalities like obesity, hyperglycemia, IR, liver injury, and changes in AKT, STAT3, and STAT6 pathways." (PMID 41007770, 2025). "In diet-induced obesity, microglial SOCS3 is elevated, but STAT3 activation in response to leptin is blunted, while NF-κB-driven inflammation persists, demonstrating selective resistance." (PMID 41516046, 2025). "Visceral adipose-derived IL-6 stimulates hepatic CRP production via STAT3 activation, creating a 2- to 3-fold increase in circulating CRP levels observed in obesity." (PMID 40699756, 2025). "An elevated level of FFAs in obesity can activate some inflammatory kinases, such as c-Jun N-terminal kinases (JNK), inhibitory-κB kinase (IKK)/NF-κB, and STAT3 in liver and adipose tissues." (PMID 40863244, 2025). "Mechanistically, reticuline inactivated the JAK2/STAT3/SOCS3 and p38 MAPK/NF‐κB signaling pathways in obesity‐related asthma." (PMID 38286741, 2024). "STAT3 activation is detected in HCC cells and is essential for the exacerbation of DEN-induced HCC in obesity." (PMID 39621069, 2024). "Our study demonstrated that loss of Tet2 in adipocytes led to the reduction of circulating leptin levels and a marked increase in basal and leptin-induced p-STAT3 levels in the hypothalamus, accompanied by resistance to HFD-induced obesity." (PMID 38561362, 2024). "Taken together, we have for the first time demonstrated that SPX alleviated diet-induced obesity and ameliorated glucose and lipid metabolism by inducing the browning of white adipose, and the pro-browning action of SPX is mediated by JAK2/STAT3 pathway." (PMID 38658956, 2024).
Obesity (continued). "In more detail, the obesity-induced oxidative environment leads to the inactivation of the T cell protein tyrosine phosphatase (TCPTP), upregulating STAT1 and STAT3 signaling." (PMID 37834153, 2023). "In the context of obesity, the oxidative hepatic environment inactivates T cell protein tyrosine phosphatase (TCPTP), a negative regulator of STAT1 and STAT3, and increases STAT1 and STAT3 activity." (PMID 37361533, 2023). "Further validation revealed that in obesity and PTC, only ELF4 and STAT3 showed high expression levels." (PMID 37671970, 2023). "It has also been shown that SOCS3 knockout mice had improved leptin sensitivity through increased hypothalamic STAT3 phosphorylation and POMC induction, while showing resistance to high-fat diet-induced obesity." (PMID 37571301, 2023). "Topological analysis and modular analysis revealed the role of HJJPD in the treatment of simple obesity by acting on SOCS-3, JAK2, LepRB, LEP, IL-6, and STAT3 and influencing the JAK2-STAT3 pathway." (PMID 35529938, 2022). "These miRNAs were suspected to target the molecules including STAT3, PI3K, AKT and FOXO1 in leptin signal in obesity, PPARγ and FOXO1 in adipogenesis pathway, and p38MAPK, PPARγ and PPARα in white adipose tissue browning pathway." (PMID 36065413, 2022). "In the context of the obesity-related breast TME, the leptin-Signal transducer and activator of transcription 3 (STAT3) axis promotes FAO and inhibits glycolysis of CD8+ Teff cells." (PMID 39872079, 2022). "The expression levels of LEPRB, SOCS-3, JAK2, and STAT3, and the key targets in the JAK2-STAT3 signaling pathway in liver and adipose tissue of mice in each group, were analyzed to verify the mechanism of HJJPD in the treatment of simple obesity." (PMID 35529938, 2022). "Mutation of the STAT3-recruiting tyrosine 1138 on the LepRb prevented SOCS3 feedback inhibition of leptin signalling, while overexpression of a constitutively active version of STAT3 in POMC neurons elevated Socs3 expression and led to obesity." (PMID 34502119, 2021). "For example, obesity-induced oxidative stress plays a critical role in T cell protein tyrosine phosphatase (TCPTP) inactivation, leading to interference in STAT-1 and STAT-3 signal transduction and the development of NASH to HCC." (PMID 34583662, 2021). "Accordingly, in vivo experiments have confirmed that obesity can affect the function and number of CD8+ immune cells through the related STAT3 pathway, metabolite GATM and ACSBG1 gene." (PMID 34901155, 2021). "It was found that the mRNA expression levels of STAT3, CORO1C, SERPINH1, MVP and ITGB5 were significantly increased in the obesity compared with the control group." (PMID 34248836, 2021). "Obesity promotes hepatic STAT1 dependent T-cell infiltration, NASH and fibrosis as well as NASH-independent STAT3-dependent HCC." (PMID 33987528, 2021). "Obesity protects lungs from VILI by upregulating SOCS3, thus suppressing the STAT3/NFκB inflammatory pathway and enhancing WNK4-related AFC." (PMID 34489970, 2021). "A previous study demonstrated that upregulated MIR20B levels in obesity-induced metabolic disorders such as T2DM were considered to prevent several targets, such as STAT3, CD36, and PTEN, which are involved in glucose and lipid homeostasis." (PMID 34964438, 2021). "In diethylnitrosamine (DEN) mice model, obesity and chronic inflammation enhanced production of IL-6 and TNF and promoted HCC development through activation of the oncogenic transcription factor STAT3." (PMID 30970564, 2019). "In this context, pro-inflammatory and growth factors secreted under obesity provide the push for sustained Kras activation and its downstream NF-κB, COX2 and STAT3 signaling, which are corroborated by animal studies." (PMID 30567335, 2018).
Obesity (continued). "In our studies, IL6 upregulation, seen after BP3 treatment, matches with improved insulin sensitivity, obesity and steatosis in IL6 transgenic mice, likely by suppressing gluconeogenic and lipogenic enzymatic cascade via hepatic STAT3 phosphorylation." (PMID 30374109, 2018). "Studies revealed that obesity-induced thyroid tumor growth and cancer progression are mediated by the activated phosphorylation of oncogenic JAK2 and STAT3 transcription factors." (PMID 28750624, 2017). "Obesity-induced thyroid tumor growth and cancer progression have been shown to be mediated by the enhancement of phosphorylation of oncogenic JAK2 and STAT3 transcription factors." (PMID 27050378, 2016). "QTL for NVD was homologous with HSA 17q21 regions which contained many obesity candidate genes including PPY, PON1 and 2, GAST, PNMT, STAT3 and HCRT." (PMID 23977060, 2013). "In conclusion, we show that POMC neurons of DIO mice are resistant to STAT3 activation by leptin and that over-expression of LepRb only in POMC neurons is sufficient to potentiate the development of diet-induced obesity." (PMID 22276206, 2012). "Indeed, elevated leptin levels, a surrogate of hyperleptinemia seen in individuals with obesity, markedly enhance the proliferation, migration, and EMT of BC cells through STAT3 activation and NCOA1 upregulation." (PMID 41562922, 2026). "Mice lacking STAT3 in POMC neurons develop obesity due to impaired satiety signaling, whereas constitutive STAT3 activation in AgRP neurons suppresses food intake." (PMID 40704145, 2025). "For example, bioinformatic comparison of transcriptomes in polycystic ovary syndrome (PCOS), obesity, and T2DM identified jointly dysregulated genes (including IGF2R, the insulin-like growth factor 2 receptor) and network “hub” proteins such as STAT3, IL1B, and PF4." (PMID 41303351, 2025). "The integration of metabolomics and network pharmacology has identified six hub targets, namely AKT1, EGFR, ESR1, STAT3, IGF1, and MAPK1, that may be critical for the effects of EGCG on obesity-related precocious puberty." (PMID 40807299, 2025). "MMe were first described as an obesity-induced ATM state in adipose depots driven by saturated free fatty acids and NOX2-dependent metabolic activation that secretes IL-6 and promotes cancer stem-like properties via GP130/STAT3 signaling." (PMID 41310829, 2025). "Key pathways linking obesity and cancer include PI3K/Akt/mTOR and JAK/STAT3 activation." (PMID 41502515, 2025). "We further tested whether targeting Stat3 in myeloid cells could inhibit macrophage infiltration into the VAT and reverse obesity-induced insulin resistance." (PMID 40801626, 2025). "Meanwhile, the mice with Stat3+/+ and Stat3−/− macrophages exhibited similar obesity when fed an HFD (data not shown)." (PMID 40801626, 2025). "The most involved anti-obesity proteins include EGFR, STAT3, JUN, GSK3B, PPARG, and HSP90AA1." (PMID 38674532, 2024). "This unique feature imparts antioxidant protection to noncancerous tissues, making DAP compounds a potentially safe inhibitor for EV regulating oncogenic proteins (STAT3, FAS, and TMEM205), with applications in preventing obesity-mediated EC and other cancers within an obese microenvironment." (PMID 39414985, 2024). "Interestingly, PRMT2 knockout mice are lean, less prone to develop diet-induced obesity and have reduced glycogen stores suggesting that PRMT2-dependent methylation of STAT3 on R31 plays a positive role in obesity." (PMID 39680066, 2024). "By increasing leptin levels, obesity alters adipose tissue macrophages’ (ATMs) metabolism through Janus kinase 3 (JAK3) and STAT3, and PI3K-Akt-mTOR pathways, increasing glycolytic enzymes’ activity and glucose uptake as well as inducing mitochondrial dysfunctions." (PMID 38558823, 2024).
Obesity (continued). "In summary, these results demonstrate that obesity conditions enhance LIFR downstream signaling and increase invasion in TNBC cells, as evidenced by increased STAT3 reporter activity, increased LIFR target gene expression, elevated levels of signaling proteins, and enhanced invasion." (PMID 39518071, 2024). "Additionally, we further demonstrated the inhibitory effects of reticuline on the JAK2/STAT3/SOCS3 and p38 MAPK/NF‐κB signaling pathways in the HFD and OVA‐induced obesity‐related asthma models." (PMID 38286741, 2024). "Despite these reported health benefits, it is unclear whether WG could activate the STAT3-AMP pathway in the jejunum and influence adipose tissue inflammation observed in obesity-induced insulin resistance, especially using a Western diet model." (PMID 37181127, 2023). "Meanwhile, leptin-induced STAT3 phosphorylation was significantly impaired under Slc7a5 deficiency in LepR-expressing VMH neurons, but not in ARC neurons, prior to the onset of obesity." (PMID 36862514, 2023). "The integrated metabolomics and network pharmacology indicated that AKT1, EGFR, ESR1, STAT3, IGF1, and MAPK1 may be key targets for EGCG in preventing obesity-related precocious puberty." (PMID 37334310, 2023). "However, the long-term usage of the inhibitors of mTORC1 increases interleukin-6 (IL-6) production, activates the signal transducer and activator of transcription 3 (STAT3), and facilitates HCC development in a murine obesity liver model." (PMID 36768977, 2023). "EGCG may contribute to preventing obesity-related precocious puberty through targets such as AKT1, EGFR, ESR1, STAT3, IGF1, and MAPK1 and multiple signaling pathways, including the estrogen, PI3K-Akt, MAPK, and Jak-STAT pathways." (PMID 37334310, 2023). "In summary, EGCG may serve a role in preventing obesity-related precocious puberty through targets such as AKT1, EGFR, ESR1, STAT3, IGF1, and MAPK1 that acted on multiple signaling pathways, including the estrogen, PI3K-Akt, MAPK, and Jak-STAT pathways." (PMID 37334310, 2023). "According to the results of integrated metabolomics and network pharmacology, 6 hub targets, including AKT1, EGFR, ESR1, STAT3, IGF1, and MAPK1, may play significant roles in the effects of EGCG on obesity-related precocious puberty." (PMID 37334310, 2023). "This increase may be secondary to an increase in leptin, often elevated in obesity, leading to increased CD8+ T cells and STAT3, which is both a signal transducer and activator of transcription." (PMID 35326592, 2022). "In another study of obesity-related KOA, Jiang found that RES attenuated obesity-related KOA by attenuating the janus kinase 2 (JAK2)/STAT3 signaling pathway independent of the suppressor of cytokine signaling 3 (SOCS3) pair." (PMID 35959426, 2022). "Obesity-related oxidative stress leads to the recruitment of T cells accompanying NASH, fibrosis along with HCC through inactivation of STAT-1 and STAT-3 phosphatase T cell protein tyrosine phosphatase (TCPTP) and activation of STAT-1 and STAT-3 signaling." (PMID 36457551, 2022). "In the absence of LepRb-STAT3 signalling, leptin is unable to exert its anti-obesity effects, but is still able to exert its permissive fertility effects." (PMID 34502119, 2021). "Paradoxically, IL-6/STAT3 signaling was required for M2-like ATM proliferation in obesity and could thus retard obesity-related insulin resistance in mice." (PMID 34504646, 2021). "Further studies confirmed their findings and identified that resveratrol alleviating obesity-related osteoarthritis via alleviating JAK2/STAT3 signaling pathway, which independent of SOCS3." (PMID 34215299, 2021). "Circulating leptin levels are increased in obesity and, with prolonged exposure, leptin can induce its own negative feedback loop via STAT3-dependent SOCS3 accumulation." (PMID 35111163, 2021).